CD4 (CD4 molecule)
Diseases named in the same sentence as CD4 in open-access papers (continued):
Sharing a sentence is not in itself a finding about the gene and the disease.
autoimmune disease (continued). "It has been shown that TLR2 signaling in CD4+ T lymphocytes promotes Th17 responses in an autoimmune disease mouse model." (PMID 29218046, 2017). "CD4+ T cells can play significant roles in common autoimmune diseases such as rheumatoid arthritis and systemic lupus erythematosus." (PMID 28225889, 2017). "Integration of GWAS signals with cell-specific chromatin marks has highlighted the role of regulatory variation in immune cells, and in particular CD4+ T cells, in autoimmune diseases." (PMID 28870212, 2017). "CD4+CD25highFoxP3+ Tregs can prevent autoimmune diseases by maintaining the tolerance to self-antigens." (PMID 29123529, 2017). "CD40-CD154 interaction is critically involved in autoimmune diseases, and CD4 T cells play a dominant role in the Experimental Autoimmune Encephalomyelitis (EAE) model of Multiple Sclerosis (MS)." (PMID 28192476, 2017). "CD4+ T cells are essential in the immune response, and Th1 and Th17 cells are most extensively studied for understanding inflammation and autoimmune diseases." (PMID 28095433, 2017). "Concordantly, differences in DNA methylation of immune-related genes have been observed in CD4+ T cells from autoimmune disease patients compared to healthy controls." (PMID 28870212, 2017). "The development of autoimmune diseases when CD4+CD25+ cells are depleted in normal rodents or when rodents and humans have mutated FoxP3 genes highlights the role of Tregs in the prevention of such diseases." (PMID 29123529, 2017). "Several studies have demonstrated that B10 can inhibit Th1/Th2/Th17 responses and promote CD4+CD25− Teff converting into CD4+CD25+ Treg in autoimmune diseases in vitro." (PMID 28831210, 2017). "In EAE, a CD4+ T cell-mediated autoimmune disease and a well-established model of MS, data indicate that separate B cell subsets regulate the induction and recovery of autoimmune neuroinflammation." (PMID 28103949, 2017). "CD4 CTLs have also been detected during antitumor responses and chronic inflammatory responses such as autoimmune diseases." (PMID 28280496, 2017). "CD4+ T cells secreting interleukin-17 (TH17) have diverse functions in modulating autoimmune diseases." (PMID 29150604, 2017). "CD4 T-helper (Th) lymphocytes are central in regulating host immune responses as well as inflammatory and autoimmune diseases." (PMID 28467798, 2017). "Myelin basic protein (MBP) peptide 1–9 was recognized by auto-reactive CD4 T cells and prevented the induction of an autoimmune disease." (PMID 28455817, 2017). "Major histocompatibility complex class II (MHCII)-restricted antigen priming of CD4+ T cells is both involved in adaptive immune responses and the pathogenesis of autoimmune diseases." (PMID 28769925, 2017). "On the contrary, the immune system of patients with autoimmune diseases is sometimes in an active state, such as an increase in Th1, CD4+, and CD25+ T cells." (PMID 28415697, 2017). "Dendritic cells (DC) initiate the differentiation of CD4+ helper T cells into effector cells including Th1 and Th17 responses that play an important role in inflammation and autoimmune disease pathogenesis." (PMID 28878767, 2017). "As regards autoimmune diseases, expansions of so-called “CD4+CD28null” (synonymous for CD4+CD28−) were described in rheumatoid arthritis (RA) patients almost 20 years ago." (PMID 28303136, 2017). "Despite the relevance of CD4 T cell polarisation and effector function in human autoimmune diseases, the expression profile of PTPs during T helper polarisation and restimulation at inflammatory sites has not been assessed." (PMID 28393080, 2017). "In a previous study, CD4+CD25− Tc cell-transferred nude mice developed multiple organ-specific autoimmune diseases and produced ANAs and anti-parietal cell antibodies, which were suppressed by CD4+CD25+ Treg cells." (PMID 28443628, 2017). "Rheumatic heart disease (RHD) is an autoimmune disease where cross reactive CD4+ T cells are involved in the pathogenesis of valvular damage." (PMID 28143491, 2017).
autoimmune disease (continued). "During the development of autoimmune diseases, including RA, CD4+ T cells (especially Tfh cells) and B cells are essential for the production of autoantibodies." (PMID 28680422, 2017). "These regulatory “killer” B‐cells are CD19+IgM+ and induce apoptosis of CD4 T‐cells, and thus have a positive effect during autoimmune disease." (PMID 28250925, 2017). "PD-L1 is also critical to inhibiting autoimmune diseases through suppression of CD4+ T cell activation." (PMID 29138509, 2017). "Tumor growth cannot be assessed in Foxp3KO mice, as they die of lethal CD4-driven autoimmune disease by 4 wk of age." (PMID 28646041, 2017). "MHCII-restricted autoantigen priming of CD4+ T cells is thought to play a role in the pathogenesis of a number of autoimmune diseases." (PMID 28769925, 2017). "Consistent with the protective effects in pSS and other autoimmune diseases, a slight decrease in CD4+/CD25+ Treg cells was observed in patients with pSS." (PMID 28886713, 2017). "Prostaglandin E2 (PGE2), a major lipid mediator abundant at inflammatory sites, acts as a proinflammatory agent in models of inflammatory/autoimmune diseases by promoting CD4 Th1/Th17 differentiation." (PMID 28604806, 2017). "Th17 and regulatory T cells, involved in the pathogenesis of several autoimmune diseases, are new lineages of CD4+ T helper cells." (PMID 28091550, 2017). "Tregs reduce tissue damage by limiting the immune response following infection and regulate autoreactive CD4+ effector T cells (Teffs) to prevent autoimmune diseases, such as type 1 diabetes (T1D)." (PMID 27727279, 2016). "Autoreactive CD4+ T cells are essential for the pathogenesis of several ab-mediated autoimmune diseases by providing help to autoreactive B cells resulting in the production of antigen-specific auto-ab." (PMID 26872212, 2016). "Both CCR6 and CXCR3 expressing CD4+ T cells have been identified in the synovial fluid of rheumatoid arthritis patients as well as in tissue samples of patients with other autoimmune diseases, such as multiple sclerosis." (PMID 27467144, 2016). "Recently, a group of CD4+T cells found in multiple inflammatory diseases and autoimmune diseases, which can secrete IL-17, has been named: Th17." (PMID 27581210, 2016). "CD4+CD25+Tregs play an important role in maintaining tolerance to self-antigens controlling occurrence of autoimmune diseases, and decreased frequency and reduced function of Tregs are associated with SS patients." (PMID 27699412, 2016). "The extracts of Brazilian propolis were benefited to control the unbalanced cytokine networks of Th1 cells via suppressing the differentiation of Th1 cells and the generation of IFNγ-producing CD4 T cells in an autoimmune disease model." (PMID 28344896, 2016). "Psoriasis is an organ-specific autoimmune disease and it is a chronic inflammatory condition characterized by hyperproliferation of keratinocytes, dermal infiltration of activated CD4+ T cells, and lesional production of proinflammatory cytokines." (PMID 27089880, 2016). "Monoclonal antibodies (mAbs) against CD4 have previously been tested for the treatment of autoimmune diseases, including RA." (PMID 26834751, 2016). "MS is an inflammatory and demyelinating disorder of the central nerve system (CNS), and current studies have found that both Th1 and interleukin-17A (IL-17A)-secreting CD4 (Th17) lymphocytes are involved in the pathogenesis of this autoimmune disease." (PMID 27809910, 2016). "Mature CD4+ T cells, especially self-reactive CD25+CD4+ T cells can prevent the development of autoimmune disease because they can fill the niche efficiently." (PMID 26215792, 2016). "CD4+CD25+ Tregs account for 5–10 % of the CD4+ T cell panel in healthy humans and mice, which is sufficient to maintain immune homeostasis and limit autoimmune disease." (PMID 27770815, 2016).
autoimmune disease (continued). "CD4+ Th17 are heterogeneous in terms of cytokine production and capacity to initiate autoimmune diseases, such as experimental autoimmune encephalomyelitis (EAE)." (PMID 27189410, 2016). "Finding an association between the expressions ofmarkers for two of the most critical cells in autoimmune diseases (Th17 and Treg) and transcript levels of miR-223 in CD4+ T-cells wouldexpand our knowledge about the developmentof MS." (PMID 27602319, 2016). "The initiation of T cell mediated autoimmune diseases such as multiple sclerosis (MS) requires the initial inappropriate activation and differentiation of auto-reactive CD4+ T cells." (PMID 27386265, 2016). "In particular, it would be of high interest to analyze the presence of CD4+CD28− T cells, which have been implicated in both autoimmune diseases like rheumatoid arthritis, MS and Graves’ disease, but also specifically in relation to CMV infection." (PMID 26956521, 2016). "Follicular helper T (Tfh) cells are a subset of CD4+ Th cells that are specialized in helping B cell responses to produce antigen-specific antibodies such as IgA, IgE, IgG and IgM in autoimmune diseases, infectious diseases, and tumors." (PMID 27769184, 2016). "MS has long been known to be a CD4 T-cell mediated autoimmune disease that targets myelin-based protein (MBP), a protein found specifically in myelin sheaths." (PMID 27809910, 2016). "Th17 cells are a subset of CD4+ T cells known to play a central role in the pathogenesis of many autoimmune diseases, as well as in the defense against some extracellular bacteria and fungi." (PMID 27695083, 2016). "Taken together, these studies demonstrate that Hrd1 is a positive regulator of human CD4 T-cell activation and differentiation, and that the elevated Hrd1 expression is involved in human autoimmune disease." (PMID 27417417, 2016). "In the present study, we demonstrated that autoreactive CD4+ induced IELs exhibit suppressive activities against a T cell-mediated autoimmune disease, that is, EAE." (PMID 27198196, 2016). "Taken together, it is reasonable to postulate that CD4+ T cells with autoimmune TCRs in the gut epithelia have a physiological role in the regulation of autoimmune diseases." (PMID 27198196, 2016). "CD4+ T cells are critical for defense against a wide array of invading microbes and pathogens but are also major drivers of autoimmune diseases." (PMID 27851911, 2016). "Multiple sclerosis (MS) is a chronic CNS autoimmune disease characterized by inflammation, demyelination, and neuronal degeneration, where myelin-specific CD4 T cells play critical roles in the formation of acute MS lesions and disease progression." (PMID 27912762, 2016). "Treg CD4+CD25+ cells from normal syngeneic mice supplied to athymic animals inhibited progression of autoimmune disease." (PMID 27156107, 2016). "In the two model autoimmune diseases discussed in this paper, there is a clear connection between MHCII polymorphisms and recognition by CD4+ T cells, resulting in autoimmune disease." (PMID 27534821, 2016). "Type 1 diabetes (T1D) is a CD4+ T cell-driven autoimmune disease resulting from the destruction of insulin-producing pancreatic beta cells." (PMID 27656680, 2016). "The conditional deletion of miR-31 in CD4+ T cells resulted in enhanced induction of pTreg cells in the periphery, and decreased severity of autoimmune disease." (PMID 26165721, 2015). "Hypermethylation of the ITGAL promoter region has also been observed in CD4+ T cells from other autoimmune diseases." (PMID 25986394, 2015). "CD4+ T cells producing IL–17 are related to inflammatory reactions in many autoimmune diseases, which have been defined as Th17 cells." (PMID 26444423, 2015). "We found that PD-1-Fc increased the percentage of CD4+IFN-γ+ and CD4+IL-17+ cells, suggesting that sPD-1 has the ability to promote Th1/Th17 cells, which are critical pathogenic T cells in autoimmune diseases, including RA." (PMID 26608464, 2015).
autoimmune disease (continued). "Paracrine calcitriol signaling to CD4+ T cells within tissues is likely the major pathway by which sunlight as an environmental factor exerts its influence on the emergence of an autoimmune disease phenotype." (PMID 25852682, 2015). "In vivo, anergy induction in autoreactive CD4+ T cells has been proven to control disease onset and progression in murine models of autoimmune diseases." (PMID 26441992, 2015). "Recent data suggest that stimulation of TLRs can directly expand CD4+CD25+ Treg that inhibit the onset or progression of autoimmune diseases." (PMID 26076454, 2015). "CD is an autoimmune disease prevalent in Caucasians of European descent (1 : 200–300) and is mediated by CD4 lymphocytes in response to ingested gluten in genetically predisposed individuals." (PMID 26664772, 2015). "CD4+T helper cells play a key role in the pathogenesis of inflammatory and autoimmune diseases via the production of distinctive sets of cytokines." (PMID 25969628, 2015). "Further animal and clinical trials of CD4-AshR-RORγt chimeras are necessary to evaluate the beneficial outcomes in autoimmune diseases." (PMID 26792955, 2015). "This review article sought to summarize and integrate research on vitamin D and CD4+ T-lymphocyte biology in an effort to develop a new understanding of the molecular etiology of autoimmune disease." (PMID 25852682, 2015). "CD4+CD25+ cells are critical regulators in almost all of the animal models of human organ-specific autoimmune diseases, transplant rejection and allergic diseases." (PMID 26564056, 2015). "Recent research has demonstrated an increasing role of newly discovered cells such as Th17 (CD4+IL-17+) or T regulatory cells (CD4+CD25+highFoxP3+) in the induction of autoimmune disorders." (PMID 26000316, 2015). "Apart from AIP, however, memory T cells (and here in particular self-antigen-reactive CD4+ effector memory T cells) have been suggested to drive the progression of autoimmune diseases because of their ready effector functionality and relative longevity." (PMID 26325540, 2015). "Functional defects in IL-10-producing CD4+ Tr1 cells have also been described in many autoimmune diseases." (PMID 25852682, 2015). "The pathogenetic role of these B19-specific CD4+ T cells secreting GrB (and possibly IL-17) in autoimmune diseases such as RA and SLE warrants further study." (PMID 26246896, 2015). "Regulation of plasticity between these CD4+ T-cell lineages is critical for immune homeostasis and prevention of autoimmune disease." (PMID 25769610, 2015). "The Th17 cell, differentiated from CD4-positive T cells, belongs to a subgroup of T-lymphocyte and contributes importantly to inflammation and autoimmune diseases." (PMID 25861246, 2015). "Recent research has demonstrated a prominent role of newly discovered cells such as Th17 (CD4+IL-17+) or Treg lymphocytes (CD4+CD25+highFoxP3+) in the induction of autoimmune disorders." (PMID 26000316, 2015). "Meaning of global DNA hypomethylation in autoimmune diseases has been best studied in systemic lupus erythematosus (SLE) CD4 T cells." (PMID 26330155, 2015). "The ability of indirubin to significantly increase thymus derived and peripheral CD4+CD25+Treg cells makes it attractive as a favored medication for autoimmune diseases or induction of transplantation tolerance." (PMID 26571298, 2015). "Our recent studies show that CD4+CD25+ Tregs are critical in preventing autoimmune diseases by suppressing self-reactive T cells." (PMID 26347149, 2015). "Th17 cells are now defined as a separate CD4+ T-cell subset distinct from the Th1 and Th2 cells, driving inflammatory responses in several T-cell driven autoimmune diseases." (PMID 25969628, 2015). "CD4+CD25+ Tregs can suppress the potential autoreactive T cells in a positive manner and protect the body from CD4+ T cell-mediated autoimmune diseases." (PMID 26347149, 2015).
autoimmune disease (continued). "This review summarizes and integrates research on vitamin D and CD4+ T-lymphocyte biology to develop new mechanistic insights into the molecular etiology of autoimmune disease." (PMID 25852682, 2015). "Despite this discovery, the modulatory effects of ex vivo-generated tolerogenic BMDCs, produced under GM-CSF protocol, have been extensively studied on CD4+ T cells in murine models of autoimmune diseases and transplantation." (PMID 26441992, 2015). "It has been well accepted that CD4+CD25+ cells are key regulators of human organ-specific autoimmune diseases, transplant rejection and allergic diseases." (PMID 26564056, 2015). "B-cell depletion impairs adaptive and autoreactive CD4-positive cells in mice, as one mechanism for observed clinical benefit of rituximab in presumed T-cell mediated autoimmune diseases." (PMID 26132314, 2015). "CD4-AsiCs overcome the hurdle of in vivo siRNA delivery to the immune cells and hold a promise to study immune responses and develop therapeutics in autoimmune diseases." (PMID 26792955, 2015). "Multiple sclerosis (MS) is an autoimmune disease driven by CD4 T cells of the T helper (h) 1 and/or Th17 subtype." (PMID 26347600, 2015). "Altered CD4+ T-cell activation and cytokine production result in chronic inflammatory conditions and autoimmune disorders." (PMID 25884400, 2015). "CD8 Treg suppress responses of both CD8+ and CD4+ T cells, and they have been shown to play a role in a number of autoimmune diseases." (PMID 26429871, 2015). "Previous studies have shown that EAN belongs to the group of CD4+ T cell-mediated autoimmune diseases that can be transferred to naïve animals by CD4+ P2-reactive T cells." (PMID 26528293, 2015). "MS is widely considered to be an autoimmune disease due primarily to CD4+ T-cell mediated immune responses to the major myelin proteins, myelin basic proteins (MBP) and proteolipid proteins (PLP)." (PMID 26295036, 2015). "On the contrary, ICOS overexpression induces overproduction of CXCR5+CD4+TFH cells and causes exuberant GC responses and remarkably promotes antibody production with autoimmune disease in mice." (PMID 26491701, 2015). "CD4+ T-helper cells that produce interleukin-17 (Th17 cells) are characterized as pathological T-helper cells in autoimmune diseases." (PMID 26368822, 2015). "Th17 cells, characterized by a CD4+IL-17A+ phenotype, have initially been described in immune response to parasites and subsequently in autoimmune diseases and inflammation." (PMID 26176858, 2015). "The aim of the review is to discuss how the AhR signaling pathway is involved in the process of autoimmune disease and immune regulatory effects on inflammation mediated by CD4 helper T cell subsets." (PMID 24905409, 2014). "There are also several pieces of evidence that epigenetic processes regulate the activity of self-reactive CD4+ T cells that mediate autoimmune disease." (PMID 24696780, 2014). "Cytokines secreted by APC play an important role in governing the activation and differentiation of CD4+ T cells in autoimmune disorders." (PMID 25144738, 2014). "MS is considered a prototypic CD4+ T helper cell-mediated demyelinating autoimmune disease of the central nervous system (CNS)." (PMID 24667731, 2014). "We demonstrate that an aberrant CD4 T cell division profile is shared by all three autoimmune strains, a finding that implicates the quality of CD4 T cell activation as a crucial determinant of autoimmune disease progression." (PMID 25171173, 2014). "CD4+ T cells, such as Th1 and Th17 cells, play a complicated and important role in inflammatory and autoimmune diseases." (PMID 24404171, 2014). "Th17 cells are a subset of CD4+ T cells that can secrete IL-17, IL-22, IL-6, and TNF-α, and have been implicated in autoimmune diseases, including multiple sclerosis, lupus, inflammatory bowel disease, RA, IDDM, and experimental autoimmune encephalomyelitis." (PMID 24586733, 2014).